NOX4 (NADPH oxidase 4)
Diseases named in the same sentence as NOX4 in open-access papers (continued):
Sharing a sentence is not in itself a finding about the gene and the disease.
diabetes (continued). "Distinct roles of NOX1 and NOX4 in modulating immune cell composition and VSMC morphology within atherosclerotic plaques in diabetes have been demonstrated in later studies." (PMID 40076813, 2025). "Preclinical studies demonstrated its dual renoprotective and atheroprotective effects in Apoe+ mice with STZ-induced diabetes, with NOX1 inhibition reducing atherosclerosis and NOX4 deletion unexpectedly increasing plaque area." (PMID 40076813, 2025). "Since NOX4 and NOX5 are both endogenously expressed in humans, we examined if Nox4 deletion is sufficient to protect against kidney damage in diabetes in the presence of NOX5 expression." (PMID 38671844, 2024). "Likewise, loss of periostin suppressed diabetes-triggered upregulations of the pro-hypertrophic genes (ANP, BNP, β-MHC), pro-fibrogenic genes (Col I, Col III, α-SMA), pro-inflammtory genes (IL-1β, IL-6, TNF-α) and pro-oxidative genes (NOX2, NOX4, 12-LOX) at the mRNA levels." (PMID 37993768, 2023). "This was evidenced by the reduction of albuminuria, glomerulosclerosis and mesangial expansion and decreased diabetes‐induced expression of glomerular VEGF, collagen IV and fibronectin in diabetic NOX4−/−ApoE−/− mice versus diabetic NOX4+/+ApoE−/− mice." (PMID 36658776, 2023). "The results of this study show that diabetes induction increases IR, urine volume, water consumption, GFR, urine glucose, urine albumin, urine urea, and kidney NOX4 and ICAM1 gene expressions in both female and male mice, as well as in the offspring." (PMID 36755074, 2023). "We evaluated the physiological parameters and renal medullary expression of TGF-β1, fibronectin, and NOX-4 in male and female mice with streptozotocin (STZ)-induced diabetes mellitus over the course of 6 days following STZ treatment." (PMID 36978977, 2023). "As a result, we showed that angiogenesis, NOX4 and SIRT1 protein levels decrease in the cardiac tissue in the early stage of diabetes." (PMID 36721814, 2023). "The key sources of oxidant stress in diabetes appear to be structurally damaged mitochondria processing excess substrate, activated NADPH oxidase complexes (particularly NOX2 and NOX4), and uncoupled endothelial nitric oxide synthase (eNOS)." (PMID 36135209, 2022). "In the present report, we have shown that diabetes was able to increase the mRNA expression levels of NOX2 in both types of muscles and NOX4 only in the EDL fibers." (PMID 35629342, 2022). "Among them, the Nox1/Nox4 inhibitor GKT137831 is the most advanced compound and has already reached phase II of clinical trials for the treatment of type 1 diabetes mellitus." (PMID 35740059, 2022). "Diabetes also induced significant increases in the number of NOX2+ (cerebrum: 34 ± 3, p = .003; cerebellum: 18 ± 2, p = .003) and NOX4+ (cerebrum: 63 ± 4, p < .0001; cerebellum: 52 ± 9, p = .02) blood vessels/cm2 compared with controls." (PMID 35488737, 2022). "Administration of the dual Nox1/Nox4 inhibitor, GKT137831, in mice models upon induction of diabetes has been shown to attenuate the diabetes induced increases in atherosclerotic plaque area." (PMID 33396868, 2020). "Nox2 and Nox4, members of NADPH oxidase family of proteins, play an essential role in vascular endothelial dysfunction in diabetes." (PMID 32024241, 2020). "We conclude that NOX4/UCP2/NF-κB and Sirt1/FOXO3a signaling pathways mediate the renal effects of PRR in diabetes." (PMID 31406124, 2019). "NOX4 is the only NOX isoform identified with mitochondrial localization, and it can be postulated that NOX4-derived H2O2 in obesity and diabetes promotes excess mitochondrial ROS production, a phenomenon termed ROS-induced ROS release." (PMID 31382355, 2019). "Collectively, these data strongly suggested that long-term diabetes conditions upregulated MCP-1, MMP-9, NOX2, and NOX4 via ERK2/3 phosphorylation." (PMID 30308936, 2018). "We previously reported that Nox4 is a major isoform of NADPH oxidase in retinal endothelial cells and its expression is upregulated by diabetes." (PMID 25866826, 2015).
diabetes (continued). "In Apoe+ mice with STZ-induced diabetes, genetic deletion of Nox1 or pharmacological inhibition using GKT137831 (setanaxib, a dual NOX1/NOX4 inhibitor) significantly reduced atherosclerotic burden, as evidenced by decreased plaque area and improved plaque morphology." (PMID 40076813, 2025). "Here, we aimed to investigate specific influence of NOX4-dependent signalling on CB-ECFC angiogenic dysfunction observed upon exposure to both experimental and clinical diabetes to define whether NOX4 may represent a viable therapeutic target in this context." (PMID 40457435, 2025). "Since individuals with diabetes develop both renal and vascular complications simultaneously, targeting solely NOX4 systemically is neither desirable nor recommended." (PMID 38671844, 2024). "By contrast, despite Nox4 deletion, diabetic mice showed renal upregulation of these ECM components in comparison to their respective non-diabetic counterparts, with these components further upregulated by EC-NOX5 expression and diabetes." (PMID 38671844, 2024). "It was demonstrated that EC-NOX5 expression further enhanced diabetes-induced increased albuminuria, inflammation, and fibrosis, as well as the upregulation of ROS-sensitive factors, regardless of NOX4 expression." (PMID 38671844, 2024). "In the vasculature, neither Nox1 nor Nox4 gene expression was affected by either hypertension or diabetes." (PMID 37253814, 2023). "In recent years, the two most promising approaches to limiting the damage of the oxidative heart caused by diabetes are to inhibit NADPH oxidation by pharmaceutical activation of NRF2 and combined NOX1/NOX4 inhibitor GKT137831, as demonstrated in several preclinical models of diabetes." (PMID 37468902, 2023). "Diabetes increased the myocardial levels of the mRNA and proteins of NADPH oxidases NOX2 and NOX4." (PMID 28698769, 2017). "Lack of Nox4 resulted in a decrease in diabetes‐induced renal cortical ROS derived from the mitochondria and the cytosol, urinary isoprostanes, and PKC activity." (PMID 25367693, 2014). "Induction of diabetes was associated with an increase in biologically active TGF‐β1 in urine, which was partly, but not fully, reduced in the Nox4 KO‐D mice." (PMID 25367693, 2014). "Glycated hemoglobin and plasma glucose were significantly increased by diabetes, independent of deletion of Nox4." (PMID 25367693, 2014). "NOX4 is constitutively active not requiring activation by p47phox or p67phox and its expression is increased in diabetes and aging." (PMID 20668682, 2010). "Similarly, whilst CB-ECFCs exposed to experimental diabetes failed to induce NOX4 upon stimulation, cells from gestational diabetic donors showed reduced NOX4 protein expression compared with those from healthy donors, whilst NOX2 levels were not impacted." (PMID 40457435, 2025). "Taken together, these data clearly indicate that experimental diabetes limits CB-ECFC pro-angiogenic capacity, whilst suggesting that loss of NOX4 signalling may be pivotal in mediating the observed lack of migratory and tubulogenic response." (PMID 40457435, 2025). "In addition to NOX4, the induction of the NOX1, NOX2 and NOX5 isoforms has also been found to promote inflammation and endothelial dysfunction in animals with experimentally induced diabetes." (PMID 37298303, 2023). "Likewise, NOX1 and NOX4 were found to be over-expressed in db/db diabetic mice, indicating that the NOX1 and NOX4 isoforms may exert a potential role in diabetes-related macrovascular disease." (PMID 34205998, 2021). "In models of diabetes and renal fibrosis, knockout of Nox4 did not result in renal protection." (PMID 34356336, 2021). "In view of this information, it is not unreasonable to suggest that diabetes-induced elevation in skeletal muscle Nox4 expression and, henceforth, excessive ROS formation could contribute to the muscle weakness/atrophy observed in this disease state." (PMID 30510624, 2018).
diabetes (continued). "Therefore, we measured superoxide production in live renal cortical tissue slices and in isolated mitochondria in Nox4 replete and KO mice in the presence and absence of diabetes." (PMID 25367693, 2014). "Indeed, it appears that Nox4 activation is a major driving force for excess ROS generation and activation of certain PKC isoforms within the kidney, thereby promoting renal injury in diabetes." (PMID 25367693, 2014). "For Nox4, both possibilities, protection and lack of protection from albuminuria, have been reported for diabetic animals, which could be due to the use of different diabetes models (i.e., streptozotocin-induced versus ApoE knockout mice)." (PMID 32635630, 2020). "In order to examine the pathogenic role of EC-NOX5 expression in DKD independent of the NOX4 pathway, the study was conducted in both wild-type (WT) and Nox4 knockout (KO) mice with and without EC-NOX5 expression in the STZ mouse model of diabetes." (PMID 38671844, 2024). "Regardless of NOX4 expression, increased levels of albuminuria (p < 0.001) were found in all groups of mice after 10 weeks of STZ-diabetes when compared to the respective control groups." (PMID 38671844, 2024). "A different investigation involving knockout of the rat NOX gene and pharmacological inhibition of the NOX enzyme revealed that NOX4, rather than NOX1, is the principal ROS generator in diabetes-induced nephropathy." (PMID 39251935, 2024). "Regarding the NADPH oxidase system, diabetes induced an increase in both NOX2 and NOX4 mRNA that was not reversed by exercise." (PMID 28698769, 2017). "To further delineate the link between Nox4 and PKC, we assessed PKC‐α and ‐β expression in Nox4 KO mice in the presence and absence of diabetes as well as evaluating putative downstream effects of both PKC isoforms." (PMID 25367693, 2014). "To investigate if Nox4 regulates PECAM-1 expression in diabetic conditions, we induced diabetes in cKO mice and isolated BMECs from non-diabetic and diabetic cKO and WT mice after 2 months of diabetes." (PMID 38748682, 2024). "There was lower Nox4 expression in SVEC from patients with type 2 diabetes compared with patients without type 2 diabetes, whereas Nox2 protein levels were increased in SVEC from patients with type 2 diabetes compared with patients without diabetes." (PMID 34420367, 2021). "Moreover, miR-25 level was higher in SVEC of patients with diabetes, and, importantly, when we transfected SVEC from patients without diabetes with mutant IGF-1R, miR-25 expression was significantly reduced with a reciprocal increase in the Nox4 expression." (PMID 34420367, 2021).
pulmonary fibrosis (107 papers, 2012 to 2025). Chronic progressive interstitial lung disorder characterized by the replacement of the lung tissue by connective tissue, leading to progressive dyspnea, respiratory failure, or right heart failure. "NOX4 has been linked to many fibrotic disorders, including hepatic, renal, cardiac, dermal and pulmonary fibrosis." (PMID 40897757, 2025). "It was demonstrated that NOX4 deficiency or acute treatment with a NOX4 inhibitor blunted TGFβ1-induced alveolar epithelial cell death and prevented subsequent pulmonary fibrosis in a murine model of lung fibrosis." (PMID 35662702, 2022). "It has been demonstrated in NOX4-deficient mice that ROS generation by NOX4 is crucial for the induction of alveolar epithelial cell death and subsequent development of lung fibrosis." (PMID 35662702, 2022). "NADPH (reduced form of nicotinamide adenine dinucleotide phosphate) oxidase-4 (NOX4) has also been implicated as a mediator of mitochondrial dysfunction in lung fibrosis." (PMID 34207528, 2021). "Another study showed that NOX4‐deficient mice can be protected from bleomycin‐induced pulmonary fibrosis by regulating epithelial cell death." (PMID 32329577, 2020). "NOX4-deficient mice were protected from bleomycin-induced pulmonary fibrosis through modulation of epithelial cell death in vivo and decreased TGF-β1-mediated ROS production and protection from apoptosis." (PMID 29849916, 2018). "Recent data showed that NOX4 deficiency mediated either by NOX4 siRNA, NOX4 inhibition, or NOX4 deletion prevents lung fibrosis." (PMID 22648375, 2012). "Nox4 has been implicated in the mechanisms of pulmonary fibrosis, suggesting that Nox4 inhibitors may be useful in IPF." (PMID 40554265, 2025). "Our results are in line with the previous observations showing that upregulation of NOX4 is linked to several pathogenic conditions, such as idiopathic pulmonary fibrosis, chronic obstructive pulmonary disease several cardiovascular conditions and osteoporosis." (PMID 38379095, 2024). "In this work, we evaluated the expression and the balance between the anti-oxidant transcription factor Nrf2 and the oxidant NOX4 cell membrane protein since the increase in NOX4/Nrf2 ratio has been associated with lung fibrosis, important sequelae of COVID-19." (PMID 36498845, 2022). "Nox4-Nrf2 dysregulation in lung tissue impairs the redox capacity, endowing the myofibroblasts with the senescence and anti-apoptotic phenotype, which causes persistent pulmonary fibrosis." (PMID 35111363, 2022). "Since the epithelial-mesenchymal transition (EMT) or myofibrogenesis of lung epithelial cells is a hallmark of pulmonary fibrosis, a feature of silicosis, the alteration of Wnt/β-catenin signaling activity and NOX4 expression of BEAS-2B lung epithelial cells in response to silica dust was examined." (PMID 33376577, 2020). "Likewise, NOX4 is selectively up-regulated in the lungs of patients with idiopathic pulmonary fibrosis and is associated with endothelial cell dysfunction and hypoxia, two processes that can foster the further up-regulation of NOX4 expression." (PMID 27345301, 2016). "Importantly, NOX4 has been implicated in the pathology of lung fibrosis, as evidenced by the reduction of fibroblast senescence and restoration of fibrosis resolution capacity following the siRNA‐induced silencing of NOX4 in bleomycin‐challenged mice with age‐associated pulmonary fibrosis." (PMID 36658776, 2023). "Moreover, Nox4 or Nox2-deficient mice were protected from BLM-induced lung fibrosis." (PMID 36552670, 2022). "Experimentally, mice with deficient NOX4 exhibited a significantly less severe fibrotic phenotype in the lungs of a bleomycin-induced pulmonary fibrosis mouse model, suggesting that NOX4 was a potential target for treatment of pulmonary fibrosis including silicosis." (PMID 33376577, 2020).
pulmonary fibrosis (continued). "Azithromycin (AZM) has been found to inhibit autophagy and contribute to the development of pulmonary fibrosis by increasing NOX4 ubiquitination through elevated STUB1 protein levels." (PMID 40901482, 2025). "PCA has an anti-fibrotic effect against pulmonary fibrosis by downregulation of the CTGF/NOX4/ET-1 gene expression." (PMID 40637744, 2025). "For instance, Salvianolic acid B was shown to attenuate paraquat-induced pulmonary fibrosis by restoring the Nrf2/NOX4 redox balance, where Nrf2 activation suppressed NOX4 expression and downstream TGF-β1/Smad3 signaling." (PMID 40438605, 2025). "Nox4 has increased expression at the level of lung fibroblasts in patients with idiopathic pulmonary fibrosis and is essential for the production of the TGF-beta 1 effect at the level of fibroblasts." (PMID 41597294, 2025). "NOX4 inhibition has been shown to be anti-fibrotic in mouse models of the liver and pulmonary fibrosis but inactive in kidney fibrosis, while the role of NOX4 has recently been challenged in TGF-β1-induced skin myofibroblast differentiation." (PMID 40298862, 2025). "The reduction of the development of pulmonary fibrosis by this compound occurs primarily by inhibiting the differentiation of pulmonary fibroblasts by influencing the MAPK/Akt/Nox4 biological signal transduction pathway." (PMID 41597294, 2025). "Given Azithromycin’s dual function in suppressing autophagy and activating STUB1, it holds potential for therapeutic use in pulmonary fibrosis by targeting NOX4 and Smad3 degradation." (PMID 40901482, 2025). "ALA decreases the NADPH Oxidase 4 levels and reactive oxygen species generation in fibroblasts, which are known to contribute to the development of pulmonary fibrosis." (PMID 40868211, 2025). "Metabolite target analysis identified nicotinamide adenine dinucleotide phosphate (NADPH) oxidase 4 (NOX4) as a key target of DBT in regulating pulmonary fibrosis." (PMID 40206091, 2025). "The restoration of the NOX4/Nrf2 redox equilibrium by Salvia miltiorrhiza was suggested to attenuate oxidative stress and impede the development of pulmonary fibrosis." (PMID 39251935, 2024). "NOX1, NOX2, and NOX4 are involved in the initiation of liver fibrosis, while NOX4 mediates idiopathic pulmonary fibrosis." (PMID 39456409, 2024). "It has been reported that NOX4 expression is increased in pulmonary fibroblasts, and siNOX4 can inhibit bleomycin-induced pulmonary fibrosis in mice." (PMID 38720270, 2024). "In organ fibrosis, OTX015 was able to inhibit the binding of BRD4 and NOX4 promoters, reducing ROS levels in fibroblasts and attenuating pulmonary fibrosis in mice." (PMID 39215370, 2024). "NOX4 plays a role in some lung diseases, such as acute respiratory distress syndrome, chronic obstructive pulmonary disease and pulmonary fibrosis." (PMID 38720270, 2024). "There is substantial evidence that NOX enzymes are present in various models of induced fibrosis, and NOX4 plays a critical role in the development of pulmonary fibrosis." (PMID 38166847, 2024). "Collectively, this evidence suggests that BRD4 is involved in promoting NOX4 expression and mediating oxidative stress-induced pulmonary fibrosis." (PMID 39215370, 2024). "NOX4 is highly expressed in type II alveolar epithelial cells (AT2) in mouse models of pulmonary fibrosis and in patients with IPF." (PMID 38286745, 2024). "It has been suggested that intraperitoneal administration of MET attenuates BLM-induced lung fibrosis in mice via NADPH oxidase 4 (NOX4) suppression." (PMID 36817136, 2023). "Setanaxib has been shown to replicate the protective effects seen in NOX4 KO models of lung fibrosis." (PMID 36658776, 2023). "The hESC-MSC-IMRC-CM can significantly inhibit BLM-induced pulmonary fibrosis in mice by inhibiting the production of ROS and proinflammatory cytokines by regulating Nox4/Nrf2 and Tlr4/MyD88 signaling pathway, respectively." (PMID 36830999, 2023).